ENO1 (enolase 1)
Diseases named in the same sentence as ENO1 in open-access papers (continued):
Sharing a sentence is not in itself a finding about the gene and the disease.
tumor (continued). "(2021), the nuclear staining of ENO1 is associated with its isoform c-Myc promoter-binding protein 1 (MBP-1), located in the nucleus and responsible for inhibiting the transcription of c-Myc, a tumor growth promoter gene." (PMID 41179678, 2025). "In addition, ENO1 can perform different functions depending on its intracellular or extracellular location, reinforcing its functional versatility in the tumor microenvironment." (PMID 41179678, 2025). "ENO1 is involved in promoting tumor progression by enhancing various cellular functions." (PMID 40507914, 2025). "In conclusion, our study revealed that ENO1, a glycolytic enzyme, stimulates the production of the glycolytic metabolites ATP and lactate by regulating glycolysis, thereby influencing the cytosolic ATP pool and overall lactate homeostasis in tumor cells." (PMID 41168198, 2025). "Moreover, to verify the differential expression of ENO1 protein, we conducted IHC on tumor and adjacent tumor samples of FPH, and the results showed a higher H score for ENO1 in tumor tissues than in normal tissues (P < 0.05)." (PMID 38273010, 2024). "However, previous studies on T cell clones from PDA patients, showed that ENO1-specific T cell clones generated from peripheral blood or tumor biopsies displayed the same TCRB repertoire, suggesting that they can recirculate from the tumor and periphery." (PMID 39176093, 2024). "Consistent with the results from non-tumor samples, all the TIMGs that we identified (ENO1, MUC1, COL5A1, COL11A1, IL11, AIM2, JUNB) as well as FABP7, exhibited significantly or moderately elevated expression in multiple TCGA tumors, including GBM, compared to normal tissues." (PMID 39596296, 2024). "Additionally, blebbistatin treatment inhibited MYH9, resulting in cytoskeleton inhibition, corresponding changes in tumor cell morphology, and disappearance of marginal colocalization of Hsp90, ENO1, and PKM2 in tumor cells." (PMID 38874476, 2024). "Indeed, tumor‐infiltrating T cells in a mouse model of melanoma exhibited attenuated enolase 1 activity, indicating yet another glycolytic step that can be negatively impacted in the tumor microenvironment." (PMID 38922759, 2024). "Alpha-enolase (Eno1; an important enzymes in glucose metabolism) has sometimes been shown to be upregulated in tumor tissues and has been found to be inversely correlated with regulatory tumor suppressors." (PMID 38730628, 2024). "ENO1 is highly expressed when the tumor is at an advanced stage." (PMID 39576845, 2024). "Taken together, the results of the present study have indicated that anti-ENO1 combined with MET could synergistically possess anti-tumor effects." (PMID 38515460, 2024). "Additionally, ENO1 was reported to reduce tumor cell tolerance to hypoxia via the aerobic glycolysis pathway and resulted in tumor angiogenesis." (PMID 38273010, 2024). "Taken together, these findings suggest that ENO1 may play an important regulatory role in tumor immunity and that ENO1 may serve as a promising prognostic biomarker for predicting prognosis associated with the TME." (PMID 39559360, 2024). "Unfortunately, the ENO1 DNA vaccine does not eradicate the tumor; it causes an initial growth inhibition, but the tumor returns to proliferate again, especially when T regulatory (Treg) and myeloid derived suppressor cells (MDSC) are present in the tumor mass." (PMID 38824552, 2024). "In addition, K420 crotonylation of ENO1 (α enolase) promotes the proliferation, migration and invasion of CRC cells by enhancing the enzyme activity of ENO1 and regulating the expression of tumor-related gene." (PMID 39606030, 2024). "This could suggest that the epithelial cell populations found in the tumor could have different metabolic cell states reflected by ENO1 gene expression levels." (PMID 39239354, 2024). "Notably, tumor reduction was abrogated in ENO1 + PI3Kγ inhibition-treated mice in which B cells were depleted." (PMID 38824552, 2024).
tumor (continued). "In this study we verify the hypothesis that MDSC targeting, via PI3Kγ inhibition, synergizes with α-enolase (ENO1) DNA vaccination in counteracting tumor growth." (PMID 38824552, 2024). "Enolase 1 (ENO1) is a subtype of enolase, which anchored on the cell membrane and served to greatly activate plasminogen to stimulate the migration and invasion ability of tumor cells." (PMID 38515460, 2024). "Notably, elevated ENO1 expression in the tumor and aging groups significantly increased CD4-positive, α-β regulatory T cell differentiation within Type 2 T helper cells, enhancing PD-L1 expression and the PD-1 checkpoint pathway activity." (PMID 39457014, 2024). "In our samples, ENO1 was significantly expressed in the tumor and expressed at different levels the cell clusters identified, particularly in epithelial populations enriched in the tumor sample." (PMID 39239354, 2024). "We identified that the role of ENO1 in tumor pathogenesis may involve BPs, such as hydrogen peroxide reaction, HIF-1 signaling pathway, glucose metabolism, and cell division." (PMID 39576845, 2024). "Although further analysis and functional experiments are required, together these observations suggest that the genetic duplication of ENO1 could lead to its expression in the epithelial populations from the tumor and this may impact their metabolism." (PMID 39239354, 2024). "ENO1 has been shown to be highly expressed in tissue samples from a variety of tumor types." (PMID 37810778, 2023). "However, the results showed that ENO1 inhibited IL-10 mRNA levels in the early stage of tumor-conditioned medium (TCM) incubation." (PMID 36614179, 2023). "Building upon our preceding investigations, wherein several tumor-suppressive proteins, including Moesin and Enolase 1, were enriched in tumor-suppressive CM, prompting the conversion of both tumor and non-tumor cells into iTSCs, we turned our focus to the role of ALDOA." (PMID 37896207, 2023). "Notably, some of these genes have been identified as important regulatory factors in LUAD, such as ENO1, which has been previously reported to promote tumor progression in LUAD." (PMID 38008419, 2023). "Meanwhile, CAD-14 inhibited tumor growth by inhibiting ENO1 in vivo." (PMID 37959729, 2023). "ENO1 is a tumor-suppressing protein that is enriched in iTSC CM." (PMID 37056934, 2023). "PGAM1 and ENO1 are overexpressed in different cancers, while their inhibition may result in decreased tumor growth and metastasis." (PMID 37500057, 2023). "In the present study, small interfering RNA (siRNA) transfection and recombinant human ENO1 (rhENO1) stimulation were used to investigate the role and mechanism of tumor cell-derived ENO1 in the interaction between tumor cells and macrophages during OSCC progression." (PMID 36614179, 2023). "Enolase 1 has been shown to bind to the c-myc promoter and function as a tumor suppressor." (PMID 38099574, 2023). "Moreover, overexpression of ENO1, which is regulated by multiple mechanisms, can promote tumor growth and development in a myriad of cancer types 28-30." (PMID 37497003, 2023). "However, there is limited evidence supporting the link between tumor-derived paracrine ENO1 and TLR4 expression in macrophages." (PMID 36614179, 2023). "Furthermore, the inhibitory effect of KIAA1429 knockdown on subcutaneous xenograft tumor proliferation and the promoting effect on cell apoptosis were rescued by ENO1 overexpression." (PMID 37807062, 2023). "Subsequently, we explored the hypothesis that ENO1 is one of the leading regulators of the Warburg effect and thus plays a major role in carcinogenesis and tumor maintenance." (PMID 36845730, 2023). "Whether the expression or function of enolase-1 or PKM2 contribute to the anti-tumor efficacy of dietary kawain remains unclear." (PMID 36838656, 2023). "A preliminary molecular mechanism study of CAD-14 indicated that it could inhibit the p38 pathway to induce apoptosis, and suppress tumor growth by inhibiting the expression of ENO1." (PMID 37959729, 2023).
tumor (continued). "It has been shown that ENO1 expression was enhanced in many tumor cells." (PMID 36765367, 2023). "Low expression of miR-1294 can up-regulate the expression of downstream protein-coding genes microtubule nucleation factor (TPX2), IGF1R, MYC proto-oncogene, bHLH transcription factor (c-Myc) and TRL4, TRL6, TRL8, TRL9, enolase 1 (ENO1), thereby promoting the proliferation of various tumor cells." (PMID 37303740, 2023). "We believe that tumor progression is related to the promotion of glycolysis by ENO1." (PMID 35925486, 2022). "ENO1 was upregulated in multiple human tumor tissues (including SKCM)." (PMID 35925486, 2022). "However, up to now, no review has yet systematically summarized the important functions and mechanisms of ENO1 in tumorigenesis and tumor immunology." (PMID 35434271, 2022). "Moreover, ENO1 has certain tumor gene characteristics and is abnormally expressed in many human tumors, which is regulated by multiple mechanisms." (PMID 35434271, 2022). "In our study, we found that the overexpression of ENO1 could enhance the glycolytic pathway of tumor cells." (PMID 35925486, 2022). "Contributing to several hallmarks of cancer, ENO1 can doubtlessly be stamped as an oncoprotein, especially in consideration of its function in deregulating glucose metabolism and, consequently, triggering tumor proliferation and metastasis." (PMID 35434271, 2022). "This dilemma represents ENO1-targeting oncotherapies as a double-edged sword: ENO1-induced glycolysis reduction would simultaneously downregulate both host anti-tumor TILs and hostile tumor cells." (PMID 35434271, 2022). "It is acknowledged that ENO1 plays a significant role in tumor progression." (PMID 35513377, 2022). "Given that the glycolytic activity of ENO1 was closely related to the up-regulation of citrate lyase expression, indicating ENO1 might be a promoter of tumor metabolism." (PMID 35836227, 2022). "Indeed, ENO1, as a glycolytic enzyme, is a multifunctional oncoprotein, and its glycolytic function deregulates cellular energetic, sustains tumor proliferation, and is correlated with poor prognosis." (PMID 36361568, 2022). "One study reported that ENO1 affected gene transcription, cell apoptosis and differentiation, regulated expression of cancer protein C-myc through the Notch signaling pathways and thus probably contributed to tumor formation." (PMID 36295613, 2022). "An in vivo study has documented that ENO1 promotes tumor invasion and metastasis of LC." (PMID 35757505, 2022). "ENO1 mainly exists in the cytoplasm and has an important function in tumor cell glycolysis." (PMID 35925486, 2022). "This revealed that 2-DG inhibited the effect of ENO1 on EMT progression, suggesting that the regulation of tumor proliferation, migration, and drug resistance by ENO1 may be related to energy metabolism." (PMID 36620599, 2022). "In addition to participating in tumor cell metabolism, ENO1 binds F-actin and tubulin, and localizes to the centrosomes, thus indicating a potential role in cell cycle regulation." (PMID 36476328, 2022). "Additionally, critical glycolytic enzymes such as hexokinase 2 (HK2), phosphofructokinase, and enolase 1 (ENO1) were upregulated in the tumor model." (PMID 36358644, 2022). "Interestingly, downregulation of ENO1 activity represses the glycolytic activity of tumor-infiltrating CD8+ lymphocytes (CD8+ TILs), leading to their functional exhaustion." (PMID 35434271, 2022). "Activation of WNT signaling in osteoclasts, osteoblasts, and cancer cells resulted in their conversion to tumor-suppressive cells with secretomes enriched with Hsp90ab1, enolase 1 (Eno1), moesin (MSN), and ubiquitin C (Ubc), which acted as atypical tumor-suppressors." (PMID 35994202, 2022). "Therefore, by sustaining T cell levels through tumor-targeted ENO1 downregulation, tumors cannot avoid being dismantled by immune responses." (PMID 35434271, 2022).
tumor (continued). "To date, approaches to target ENO1 metabolism are based on the tumor-specific metabolic switches." (PMID 36077431, 2022). "As has been demonstrated by an in vitro study, ENO1 may serve as a tumor-promoting gene in oral squamous cell carcinoma through the circ-AMOTL1/miR-22-3p/miR-1294 network." (PMID 35434271, 2022). "While we showed that extracellular Eno1 downregulated c-Myc as well as p-Akt, p-p65, and p-Erk in tumor cells, it is unclear whether it may act as MBP1." (PMID 35547745, 2022). "Recent reports have demonstrated that ENO1 plays a critical role in various tumor progression." (PMID 35836227, 2022). "Compared with non-tumor tissues, ENO1 was found to be overexpressed in SKCM tissues." (PMID 35925486, 2022). "Research has focused on the role of ENO1 in tumor progression and cancer treatment." (PMID 36476328, 2022). "In tumor cells, ENO1 is also highly expressed on the cell surface, but the mechanism by which it switches from cytoplasm to membrane is unknown." (PMID 36612133, 2022). "The activation of the ENO1-mediated glycolytic pathway upregulates the transcription and inhibits the apoptosis of the cellular oncogene, resulting in angiogenesis and affecting the response to hypoxia in tumor cells." (PMID 35434271, 2022). "Therefore, ENO1 expression has certain significance in analyzing and conjecturing patients survival with different depths of tumor invasion and degree of venous metastasis." (PMID 36620599, 2022). "A previous study showed ENO1 contributes to tumor progression through PI3K/AKT signaling." (PMID 35513377, 2022). "Further, there are few studies on ENO1 affecting drug resistance in tumor cells." (PMID 36620599, 2022). "ENO1 played an essential role in the glycolysis process of tumor cells." (PMID 34504528, 2021). "Notably, the anti-tumor effect of 1 μg/mL of recombinant Eno1 proteins on MMT-based viability was suppressed when CD44 was silenced." (PMID 34373756, 2021). "Besides its well-known enzymatic functions, decades of research have shown that ENO1 is aberrantly expressed in multiple tumor types and participates in diverse cellular processes through non-metabolic mechanisms." (PMID 34627260, 2021). "ENO1 also localizes in the nucleus to regulate c-myc expression and impede tumor growth." (PMID 33968941, 2021). "We next examined whether iTS CM, Eno1, and Ubc may preferentially inhibit the progression of tumor cells." (PMID 34373756, 2021). "Eno1 was enriched in CM and its interaction with CD44 was involved in Eno1's anti-tumor action." (PMID 34373756, 2021). "In addition, anti-PDL1 synergized with the ENO1 inhibitor for enhancing autologous tumor-specific CD8+ and NK cell activity." (PMID 33804240, 2021). "Ectopic ENO1 overexpression promoted tumor formation and tumor chemoresistance." (PMID 33968941, 2021). "Immunoprecipitation revealed that extracellular Hsp90ab1 interacted with latent TGFβ (LAP-TGFβ) as an inhibitor of TGFβ activation, while Hsp90ab1 and Eno1 interacted and suppressed tumor progression via CD44, a cell-adhesion receptor and a cancer stem cell marker." (PMID 34830748, 2021). "Moreover, subcutaneous tumor xenograft models also showed that metformin induced the expression of CCDC65 while suppressed expression of ENO1, and si-CCDC65 treatment neutralized metformin-mediated inhibitory effect on GC." (PMID 34335983, 2021). "Overexpressed ENO1 had been observed in many tumor cells, and the upregulation of ENO1 expression might be correlated to aerobic glycolysis of cancer cells and the occurrence of malignant tumors." (PMID 34504528, 2021).
tumor (continued). "Also, western blot indicated that ENO1 protein expression levels in nude mice tumor tissues was significantly decreased in the si-HNF1A-AS1 group than in the si-NC group." (PMID 34772911, 2021). "Importantly, the partial silencing of CD44 in EO771 tumor cells reduced the inhibitory effect of recombinant Eno1 proteins on the MTT-based viability, and partially suppressed the Eno1-driven downregulation of Lrp5, Runx2, and TGFβ in EO771 tumor cells." (PMID 34830748, 2021). "We also detected the favorable tumor selectivity with Eno1 and Ubc." (PMID 34373756, 2021). "At the cell membrane, ENO1 activates the plasminogen system to accelerate tumor cell invasion." (PMID 33968941, 2021). "Compared to normal tissue, ENO1 was upregulated in tumor tissue." (PMID 34035230, 2021). "Meanwhile, there is a positive correlation between auto-antibody levels of ENO1 and expression of phosphorylated ENO1 or ENO1 in tumor tissue, suggesting that ENO1 might be a biomarker of cancer 16,102-105." (PMID 34671213, 2021). "The present study targeted the hitherto unexamined expression of ENO1 protein, using an immunohistochemical method, in tumor and matched adjacent normal tissue sections from EC patients, as well as ENO1 circulating levels; their clinical relevance was also examined." (PMID 33628097, 2021). "BM CM was enriched with atypical tumor-suppressing proteins such as Hsp90ab1 and enolase 1 (Eno1)." (PMID 34830748, 2021). "Previous studies confirmed that ENO1 took part in the proliferation of tumor cells." (PMID 34504528, 2021). "In addition, ENO1 KO also alleviated the glycolytic capacity of tumor cells treated with control neutrophils." (PMID 34312368, 2021). "ENO1, as a key glycolytic enzyme, may play pivotal role in aerobic glycolysis (the so-called Warburg effect) contributing to tumor progression of numerous cancers." (PMID 33628097, 2021). "Conversely, ENO1 silencing in tumor cells significantly decreased malignant biological behavior." (PMID 33968941, 2021). "ENO1 may be delivered into bloodstream by tumor cell necrosis and turnover or unconventional secretory pathways." (PMID 33628097, 2021). "Moreover, ENO1 is thought to be related to aerobic glycolysis levels in tumor cells and malignant tumor development." (PMID 33067426, 2020). "However, KICH tumor samples showed a significantly lower level of ENO1 compared to normal tissues (P < 0.01)." (PMID 33643901, 2020). "The ENO1 mutation analysis was performed by cBio Portal, and demonstrated ENO1 mutation (1.8%) did not impact on tumor prognosis." (PMID 33643901, 2020). "ENO1 plays a critical role in cancer proliferation, metastasis and spreading, thus therapies targeting ENO1 may be effective in hindering tumor progression." (PMID 35582441, 2020). "Thus, further studies should be performed to investigate the role of secreted ENO1 in tumor biology." (PMID 32197468, 2020). "Functionally, ENO1 could promote the stem-like characteristics of GC cells by prominently regulating tumor glycolysis." (PMID 33067426, 2020). "In addition, the enzymatic activity of ENO1 in solid tumors is regulated at posttranslational level as evidenced by the upregulated mRNA and protein expressions of ENO1 in CD8+ tumor-infiltrating lymphocytes." (PMID 33643901, 2020). "ENO1 expression in multiple tumor tissues correlated with prognosis and stage." (PMID 33643901, 2020). "Moreover, many proteomics studies based on TEXs have shown that ENO1 is selectively enriched in some TEXs, and ENO1 has thus become a potential biomarker for tumor detection." (PMID 33184263, 2020). "One explanation may be that tumor cells physically absorb and neutralize ENO1 antibodies expressed and secreted on the surface to reduce circulating levels." (PMID 33643901, 2020).